IL4R (interleukin 4 receptor)
Diseases named in the same sentence as IL4R in open-access papers (continued):
Sharing a sentence is not in itself a finding about the gene and the disease.
allergic asthma (24 papers, 2004 to 2025). A asthma with a basis in a pathological type I hypersensitivity reaction. "Furthermore, IL4R variants linked to allergic asthma were discovered to exacerbate airway inflammation by promoting regulatory T cell conversion to TH17-like cells." (PMID 36081945, 2022). "B-cell–deficient mice have significantly increased AHR at high-dose HDM, a phenotype different to what we observe in IL-4Rα–deficient B cells, which suggested that IL-4Rα–responsive B cells may be involved in driving AHR during allergic asthma." (PMID 33383090, 2021). "In addition, deletion of the gene encoding IL-4Rα rendered mice resistant to the induction of experimental allergic asthma." (PMID 23922687, 2013). "Many biologics have been developed to combat type 2 inflammation and allergic asthma, with IL-4Rα being one of the main targets, since both IL-13 and IL-4 utilize it as a receptor." (PMID 40170850, 2025). "Several new loci are relevant to immunological pathways (e.g., 5p13.2 near IL7R, 10p15.2 near IL2RA, and 22q12.3 near IL2RB), including the allergic asthma locus IL4R (ORCRSwNP = 1.151 [1.104–1.199], p = 2.54e-11)." (PMID 41213931, 2025). "Strong suppression of inflammation in allergic asthma has been achieved in phase I/II studies using interleukin-4 receptor subunit alpha (IL-4Ra) antagonists with lipocalin-1 nanocarriers." (PMID 39204164, 2024). "Currently, monoclonal antibodies targeting IL-4Rα are administered subcutaneously to treat eosinophilic rhinosinusitis and allergic asthma." (PMID 39108557, 2024). "All in all, our data demonstrated that IL-4Rα on B cells is important in TH2 allergic asthma at both sensitization and challenge stages and contributes to overall TH2 responses when the antigen load is limited." (PMID 33383090, 2021). "Overall, these results demonstrate that at low-dose HDM exposure, IL-4Rα on B cells contributes significantly to the development of allergic asthma and TH2-type lung inflammation." (PMID 33383090, 2021). "Specifically, IFN-G, IL-13, IL-5, and IL-4R showed an especially high overall relationship with allergic conditions (respiratory allergy and allergic asthma)." (PMID 33936056, 2021). "IL-4 receptor α (IL-4Rα) is key in allergic asthma and regulates type 2 cytokine production, IgE secretion, and airway hyperresponsiveness." (PMID 33383090, 2021). "IL-4Rα signaling on B cells is deleterious in allergic asthma because it is required for optimal TH2 responses, Be2 function, germinal center formation, and T follicular helper cells, especially when the load of the antigen is limiting." (PMID 33383090, 2021). "Overall, these results demonstrated that IL-4Rα on B cells plays a minimal role in the development of allergic asthma after a challenge with high-dose HDM." (PMID 33383090, 2021). "Taken together, our findings indicate that IL-4Rα–unresponsive FoxP3+ Tregs result in exaggerated innate Th2-type, IL-33–dependent airway inflammation and a break in tolerance during allergic asthma." (PMID 32931477, 2020). "Abrogation of IL‐4Rα signaling after allergic sensitization would have significant therapeutic benefit for TH2‐type allergic asthma." (PMID 31782803, 2020). "In a previous transcriptomic study, increased expression of interleukin-4 receptor (IL-4R) on B cells was observed in allergic asthma patients." (PMID 33644088, 2020). "IL‐4RαY500F mice possess a germline mutation in the Il4ra gene resulting in a loss of IL‐4Rα‐induced PI3K signaling and leading to impaired IL‐4‐induced CD4+ T‐cell proliferation, increased allergen‐induced IgE production and an allergic asthma phenotype 29." (PMID 26734464, 2015). "IL-4 is also known to suppress TH17 development in a STAT-6 dependent manner with IL-4Rα−/− mice producing increased levels of IL-17 in an allergic asthma model." (PMID 23284939, 2012).
allergic asthma (continued). "The combination of IL-4Rα (148 G/A: Val50Ile) and IL-4 (-590 C/T) was also associated with CAA (P = 0.00689); association between allergic asthma and this combination has previously been reported." (PMID 15339344, 2004). "IL-4Rα mediates allergic asthma by inducing the M2 polarization of macrophages." (PMID 40005151, 2025). "We sought to find out whether IL-4Rα–responsive B cells or Be2 function was essential in experimental allergic asthma." (PMID 33383090, 2021). "We challenged mice with high-dose or low-dose HDM to assess whether antigen load matters in the requirement of IL-4Rα–responsive B cells in allergic asthma." (PMID 33383090, 2021). "Therefore, the in vivo role of canonical IL-4 receptor α (IL-4Rα) signaling, an essential driver of Th2-type airway responses to allergens, on the regulatory function of FoxP3+ Tregs in allergic asthma was explored." (PMID 32931477, 2020). "Hence, abrogation of IL‐4Rα signaling should have significant therapeutic benefit for TH2‐type allergic asthma." (PMID 31782803, 2020). "We developed a TAM‐induced, conditional IL‐4Rα knockdown mouse model (RosacreERT2IL‐4Rα−/lox) and sought to investigate the temporal role of IL‐4Rα receptor signaling during the effector phase (therapeutic) and priming/sensitization phase (prophylactic) of allergic asthma." (PMID 31782803, 2020). "IL-4 and IL-13 via IL4Rα signaling have been known to drive MCM in 10-day-old Tg+ mice and mice models of allergic asthma." (PMID 40406132, 2025). "•IL-4Rα–responsive B cells are required for Be2 function of B cells and help maintain optimal TH2 during allergic asthma." (PMID 33383090, 2021). "Eosinophils, which are central to the pathogenesis of allergic and non-allergic asthma, express high levels of surface IL-5Rα chain, as well as TSLPR, the IL-4Rα chain common to IL-4R and IL-13R, and the high-affinity receptor FcεRI." (PMID 34572466, 2021). "Our results highlight a complex function of IL-4Rα signaling on FoxP3+ Tregs in regulating airway hyperreactivity and lung pathology during HDM-induced allergic asthma." (PMID 32931477, 2020). "We therefore provide evidence for the indispensable role of IL-4Rα signaling in maintaining Treg stability and IL-4–responsive Tregs in limiting IL-33–derived ILC2-driven AHR and airway inflammation in HDM-induced allergic asthma." (PMID 32931477, 2020). "This is consistent with our previous studies in allergic asthma where the absence of IL-4Rα on B cells led to reduced GC numbers, Tfh and IgE production." (PMID 36599893, 2023). "We showed that IL-4Rα–responsive B cells play a nonredundant role in allergic asthma in an antigen load–dependent manner." (PMID 33383090, 2021). "In this report, we show that lack of IL-4Rα signaling on Tregs, in the context of HDM-induced allergic asthma, results in uncontrolled lung pathology and airway hyperreactivity." (PMID 32931477, 2020). "IL-4 is critical in class switching of B cells to generate IgE40; however, whether signaling through the IL-4Rα on B cells is required for the generation of TFH cells and IgE has not been investigated in the context of allergic asthma." (PMID 33383090, 2021).
glioma (24 papers, 2002 to 2025). A benign or malignant brain and spinal cord tumor that arises from glial cells (astrocytes, oligodendrocytes, ependymal cells). "Under apoptosis-evading conditions of tumors, IL4 receptor (IL4R) is promoting proliferation and blockage or hypomorphic nucleotide polymorphisms in IL4R reduce the aggressiveness of glial tumors." (PMID 32181251, 2020). "Univariate analysis showed that IL4R rs1801275 was significantly associated with overall survival of glioma and astrocytoma patients (P < 0.05)." (PMID 27495027, 2016). "We showed that genetic variant GG of IL4R rs1801275 was significantly associated with poor survival of glioma and astrocytoma patients." (PMID 27495027, 2016). "Polymorphisms in the interleukin-4 receptor genes are associated with better OS in Glioma patients." (PMID 36138874, 2022). "Associations between IL4R rs1801275 and glioma and astrocytoma." (PMID 27495027, 2016). "Multivariate Cox regression analysis showed that IL4R rs1801275 GG genotype could increase the death risk of glioma and astrocytoma patients (Glioma: hazard ratio [HR]: 4.897, 95% confidence limits [95% CI]: 1.962–12.222, P = 0.001; Astrocytoma: HR: 15.944, 95% CI: 4.019–63.253, P < 0.05)." (PMID 27495027, 2016). "Studies have shown that the IL-4 receptor-α (IL-4Rα) is overexpressed in glioma-infiltrating myeloid cells, playing a key role in driving their immunosuppressive functions." (PMID 41003104, 2025). "MDNA55 is an engineered immunotoxin with permutated IL-4 conjugated to a modified pseudomonas exotoxin (PE), that targets glioma cells and immune suppressive cells highly expressing IL-4R." (PMID 37568717, 2023). "Its receptor, IL-4R, is abundantly expressed by glioma cells thereby presenting the CRKRLDRNC as a promising tool for glioma targeting." (PMID 33918106, 2021). "Different studies have reported on the importance of IL-4 and GMCSF in glioma development and/or progression, showing an enhanced risk and worse outcome of GBM for people that carry certain polymorphisms in IL-4R and STAT-6 gene loci." (PMID 34880868, 2021). "In this regard, GM-CSF, which is expressed at high levels in human gliomas, induces the upregulation of IL-4Rα on glioma-infiltrating MDSCs, thereby leading to IL-13-induced production of arginase resulting in T cell inhibition." (PMID 34948178, 2021). "Different gliomas secrete IL-4, and glioblastoma multiforme (GBM) risk and outcome are correlated to polymorphisms in IL-4R gene loci." (PMID 34880868, 2021). "MDSCs account for more than 40% of glioma-infiltrating immune cells and expressed IL-4Rα, inducible nitric oxide synthase (iNOS) and ARG1 to inhibit the responses of glioma-killer T lymphocytes and NK cells, causing patients poor prognosis." (PMID 34211978, 2021). "In recent years, tumor drugs have targeted AP1, a new glioma affinity peptide that specifically binds to IL-4R and exhibits the highest therapeutic effect on glioma." (PMID 33013320, 2020). "Therefore, IL-4R may also be a new target for glioma-associated epilepsy treatment." (PMID 33013320, 2020). "Knockdown of IL-4Rα in BALB/c mice with de novo SB transposon-induced gliomas subsequently resulted in downregulation of immunosuppressive pathways involving TGFβ, ARG1, and cyclooxygenase-2 (COX-2)." (PMID 31396227, 2019). "The 1-year overall survival of glioma patients with IL4R rs1801275 GG (0%) and GA (29.3%) were lower than the AA (31.5%) genotype." (PMID 27495027, 2016). "The 1 year OS of glioma patients with IL4R rs1801275 GG (0%) and GA (29.3%) were lower than the AA (31.5%) genotype (P < 0.05)." (PMID 27495027, 2016). "Several studies have reported that SNPs in IL-4, IL-4R, and IL-13 were inversely correlated with the incidence of glioma." (PMID 27566584, 2016). "IL4R is found in abundance in glioma tumor cells and hence IL4 along with Pseudomonas exotoxin is used as immunotoxin therapy in clinical trials." (PMID 26390214, 2015).
glioma (continued). "They showed that GM-CSF is expressed in glioma tissues and can induce IL-4Rα expression in vitro." (PMID 31396227, 2019). "CRKRLDRNC peptide, named as AP1, was a newly glioma affinity peptide which could specifically binds to interleukin-4 receptor (IL-4R), highly expressing on both glioma cells and angiogenesis." (PMID 28938600, 2017). "Therefore, IL-4R-based active targeting drug delivery could be applied for efficient glioma treatment through the receptor-mediated transcytosis." (PMID 28938600, 2017). "Upregulation of the IL‐4R (CD124) has been shown in multiple human and murine malignancies including glioma, lung, breast, pancreatic, bladder, colon, and ovarian cancers." (PMID 33682324, 2021). "For example, receptors that are highly expressed on the surface of glioma cells can allow for targeted delivery of agents into tumor BBB-disrupted regions, including interleukin-4 receptor (IL-4R), interleukin-13 receptor (IL-13R) and neurokinin-1 (NK-1)." (PMID 33198244, 2020). "Besides, previously results showed that IL4, IL4R and IL13 genes may play an important role in glioma survival." (PMID 23663500, 2013).
eosinophilia (20 papers, 2011 to 2025). "While IL-4Rα KO mice were still able to generate eosinophilia and controlled the infection, mice became susceptible after depleting eosinophils through CCR3." (PMID 36389745, 2022). "In the therapeutic regimen, blockade of IL-4Rα attenuated weight loss and reduced viral load though eosinophilia and goblet cell metaplasia persisted." (PMID 33653328, 2021). "Treatment of HDM sensitized mice with a monoclonal antibody against IL-4Rα prior to or following pH1N1 infection prevented the excess weight loss, reduced the viral load in the lungs and ameliorated airway eosinophilia and systemic inflammation related to the pH1N1 infection." (PMID 33653328, 2021). "Interestingly, myeloid-specific IL4Rα-deficient (mye-IL4Rα−/−) mice had significantly reduced eosinophilia in the airspaces that was associated with reduced levels of IL-4 and IL-5 in the bronchoalveolar lavage fluid (BALF)." (PMID 34326406, 2021). "An associated residual eosinophilia was apparent in infected IL-4Rα−/− mice." (PMID 32571840, 2020). "The largest network of eosinophilia contained two genes (IL4R, TSLP) targeted by drugs currently available for eosinophilic asthma." (PMID 37186423, 2023). "Temporal genetic deletion of the IL‐4Rα after sensitization reduced TH2 disease by abrogating effector mechanisms such as CD11b+ migratory DCs, TH2‐associated cytokines, eosinophilia, mucus production, and AHR." (PMID 31782803, 2020). "Inducible deletion of IL‐4Rα demonstrated therapeutic effects, on established allergic airway disease, and prevented the development of ovalbumin‐induced airway hyperreactivity, eosinophilia, and goblet cell metaplasia in allergen‐sensitized mice." (PMID 31782803, 2020). "We demonstrate that a residual eosinophilia occurs in B. malayi–infected IL-4Rα−/− mice, which we successfully targeted via serial treatment with anti-αCCR3 depleting Ab." (PMID 32571840, 2020). "Together these data indicate that ligation of IL-4Rα and subsequent BmL3AAMφ development augments tissue eosinophilia via CCR3 chemotaxis during the adaptive immune response to infection." (PMID 29547639, 2018). "Despite the expected IL-4Rα-dependent type 2 phenotype (i.e. eosinophilia, mucus production, and development of T1/ST2+ Th2 cells) WT mice unexpectedly more efficiently control the early fungal growth." (PMID 24475277, 2014). "There was a correlation between the number of macrophages expressing the IL-4Rα, CD11b, and IAd, and the degree of eosinophilia in ovalbumin challenged mice." (PMID 22292924, 2012). "In this model, STAT6 and IL-4Rα expression are only partially required for inducing pulmonary inflammation and eosinophilia." (PMID 22014099, 2011). "Its superior performance likely stems from its dual inhibition of IL‐4 and IL‐13 signaling via IL‐4Rα blockade, a mechanism validated in preclinical models where IL‐4Rα knockout mice exhibited reduced mucosal eosinophilia and polyp burden in house dust mite‐induced nasal polyposis." (PMID 41178615, 2025). "Importantly, STAT6–/– x IL5Tg or IL4Rα–/– x IL5Tg mice had comparable blood eosinophilia, and ILC2 expansion after IL-33 treatment was equivalent." (PMID 33974563, 2021). "Given that insufficient NLRP1 exacerbated eosinophilia and IL-13 levels in the mouse model we studied, it is conceivable that blocking this axis with agents such as IL-4Rα may work more effectively in carriers of the NLRP1 M1184V variant." (PMID 33378691, 2021). "The percent eosinophils recovered were comparable between LysMcre+/−/IL4Rαfx/wt (~ 12%) and LysMcre+/+/IL4Rαfx/wt (~ 12%) suggesting that the presence of biallelic cre and inactivation of one allele of IL4Rα does not result in a reduction in BALF eosinophilia." (PMID 34326406, 2021).
eosinophilia (continued). "The residual eosinophilia was maintained throughout the time course of infection in IL-4Rα−/− mice and was significantly elevated compared with corresponding CCR3−/−-infected animals at 5 wk (p = 0.05) or 12 wk postinfection (p = 0.05; Dunn multiple comparisons tests)." (PMID 32571840, 2020). "Temporal genetic deletion of the IL‐4Rα in an established disease reduced CD11b+ migratory DCs, eosinophilia, IgE, mucus production, AHR, but not TH2‐associated cytokines." (PMID 31782803, 2020). "However, transfer of IL-4Rα+/+ BMM resulted in an increase in airway eosinophilia in response to inhaled OVA (20%); this was further increased by OVA immunization to 55%." (PMID 22292924, 2012). "The reduced expression of FIZZ1 and YM1 in the absence of STAT6 or IL-4Rα may be functionally linked to the reduced inflammation and eosinophilia seen in STAT6xRAG2-/- and IL-4RαxRAG2-/- mice." (PMID 22014099, 2011). "Our findings show that temporal deletion of IL‐4Rα signaling postsensitization prevents development of OVA‐induced AHR, eosinophilia, and goblet cell hyperplasia." (PMID 31782803, 2020). "The parasitological outcome of IL-4/IL-4Rα activation of BmL3AAMφ and CCR3-dependent tissue eosinophilia was a significant reduction in B. malayi larvae in SCID mice +14dpi." (PMID 29547639, 2018). "Consistent with the degree of eosinophilia, the BALF levels of eosinophil recruitment-associated cytokines were significantly elevated in IL-13-treated WT but not in IL-13-treated mye-IL4Rα−/− mice." (PMID 34326406, 2021). "The absence of BALF eosinophilia in mye-IL4Rα−/− mice and associated reduction in BALF levels of IL-4, IL-5, and eotaxin suggest that IL4Rα expression in myeloid cells is essential for eosinophil recruitment." (PMID 34326406, 2021). "Like ILC2del mice, IL4Rα–/– x IL5Tg and STAT6-–/– x IL5Tg mice were protected from pulmonary hemorrhage after IL-33 administration and had dramatically reduced BAL eosinophilia compared with controls." (PMID 33974563, 2021). "In a previous investigation, we reported that macrophages polarized to an alternatively activated phenotype through IL-4R activation mediated immunity to the human lymphatic filarial pathogen, Brugia malayi, by sustaining a vigorous CCR3-dependent eosinophilia at the site of infection." (PMID 32571840, 2020). "Our data indicate that both CCR3-dependent ligands and IL-5 are necessary to induce eosinophilia to filarial infection in the absence of IL-4R signaling." (PMID 32571840, 2020). "Temporal deletion of IL‐4Rα chain after sensitization phase prevented disease development, whereas temporal deletion during the effector phase reduced most disease parameters, such as AHR, eosinophilia, as well as goblet cell metaplasia." (PMID 31782803, 2020). "Our present study illustrates that whereas a muted eosinophil response is evident in the absence of IL-4/IL-13 signaling, low eosinophilia is still an integral component of immune attrition to juvenile adults in IL-4Rα mice." (PMID 32571840, 2020). "The administration of prednisolone in this IL-4Rα-depleted mouse model led to a decrease of lymphoid infiltrates and eosinophilia but failed to ameliorate mucus plugging." (PMID 30911386, 2019). "Thus it appears that while IL-4/IL-13 signaling through IL-4Rα and STAT6 is essential for induction of AAM genes, lung inflammation and eosinophilia are only partially dependent on this pathway." (PMID 22014099, 2011). "Furthermore, while IL-4/IL-13 signaling through IL-4Rα and STAT6 is essential for AAM protein expression, lung inflammation and eosinophilia are only partially dependent on this pathway." (PMID 22014099, 2011). "We found that in the absence of STAT6 and IL-4Rα, mice developed less pulmonary inflammation, reduced perivascular and peribronchial cuffing and decreased eosinophilia than our control mice." (PMID 22014099, 2011).